CRP (C-reactive protein)
Diseases named in the same sentence as CRP in open-access papers (continued):
Sharing a sentence is not in itself a finding about the gene and the disease.
anemia (continued). "CRP is an acute phase protein produced in response to inflammation, and elevated levels of CRP have been associated with anemia and can serve as a marker for inflammation related anemia." (PMID 38799419, 2024). "LRG1 served as a serum marker associated with inflammation, indicated by CRP, anemia, hypercalcemia, and malignant potential in ccRCC." (PMID 38658967, 2024). "We assessed hemoglobin (a biomarker of anemia) with a hemoglobinometer and soluble transferrin receptor (a biomarker of iron deficiency) and C-reactive protein (a biomarker of inflammation) in dried blood spots via enzyme immunoassay." (PMID 37315072, 2023). "Two of our cases were associated with constitutional inflammatory symptoms such as fever, anemia, weight loss, and elevated serum CRP, all regressed immediately after tumor removal." (PMID 37097347, 2023). "Nevertheless, the logistic regression results also revealed that the presence of inflammation, denoted by CRP, also significantly increased the risk of anaemia." (PMID 36996088, 2023). "The most prevalent laboratory abnormalities at presentation were iron deficiency anemia in 16/20 (80%), thrombocytosis in 13/19 (60%), hypoalbuminemia in 10/19 (53%), and elevated CRP in 14/17 (83%)." (PMID 36937967, 2023). "There are three risk factors for anaemia among WRA: elevated CRP levels (inflammation indicator), IDE and ID." (PMID 36996088, 2023). "These assumptions are in line with the increased CRP and fibrinogen levels as further factors associated with anemia of chronic disease, as well as tumor-associated systemic inflammation that is linked to poor survival in lung cancer patients." (PMID 36849951, 2023). "In this study, high C-reactive protein levels were significantly associated with more severe depressive symptoms and anemia." (PMID 37553590, 2023). "Inflammatory anemia is also a common cause of anemia in hospitalized individuals and is more prevalent among those with elevated circulating inflammatory markers, such as C-reactive protein (CRP)." (PMID 36936903, 2023). "Multivariate logistic regression analysis indicated that the presence of chronic kidney disease, drug-resistant TB, baseline anemia, high initial CRP levels, and normouricemia were independently associated with worse outcomes." (PMID 37972037, 2023). "Inflammation was significantly associated with an increased risk of having anemia in both districts, with an estimated additional risk of anemia associated with inflammation (CRP or AGP) of one-fifth in Achham and 5% in Kapilvastu." (PMID 37180849, 2023). "Our study with RA patients shows that older age, abdominal obesity, elevated NT-pro BNP, c-reactive protein, troponin, and anemia were independently associated with a shorter 6MWT distance." (PMID 36333405, 2022). "During disease, IL-6 mediates fever, loss of appetite, weight loss, and anemia, and constitutes the main inductor of acute-phase proteins synthesis, including C-reactive protein (CRP)." (PMID 35634339, 2022). "Both anemia and increased CRP levels are associated with decreased overall survival and increased cardiovascular mortality." (PMID 35160156, 2022). "Both anemia and inflammation are associated with inflammatory markers high concentrations, such as C-reactive protein, which is linked to anemia treatment resistance in CKD patients." (PMID 36137129, 2022). "Our main findings demonstrate and confirm the role of hepcidin and IL-6 in the pathogenesis of lung cancer-related anaemia, as well as present diagnostic values for hepcidin, IL-6, and CRP." (PMID 36612220, 2022). "The associations of higher body mass index, anemia, higher C-reactive protein and lower plasma albumin with longer time required for performance of the 9-hole peg test suggest that overall health seems to be a major determinant of hand dexterity." (PMID 36171358, 2022). "Mucosal heterotopia (present in 39% of symptomatic MD) was associated with anemia and lowered CRP-levels." (PMID 35053658, 2022).
anemia (continued). "Still, inflammation indicated by elevated CRP was associated with poor outcome in patients with anemia and available serum iron parameters as well as in the entire patient cohort, where CRP was available in the majority of patients." (PMID 35895618, 2022). "The patient in this case presented with body weight loss, fatigue, anemia, hypoalbuminemia, and elevated CRP levels." (PMID 35765296, 2022). "On multivariate analysis age, CRP, and anemia etiology remained independent associated with survival." (PMID 35895618, 2022). "The conclusion from these results is that more refined investigations than serum iron parameters and CRP are required to better understand anemia etiology and its association with outcome." (PMID 35895618, 2022). "Moderate anaemia and log CRP were associated with elevated SHR (10.3beats/min, 95%CI: 7.3, 13.5 and 7.0 beats/min, 95% CI: 5.5, 8.6) in HIV-infected only (interaction p = 0.04 and p<0.001)." (PMID 35061774, 2022). "A low hepcidin concentration combined with a low CRP concentration (within reference values, <5 mg/L) indicates the presence of iron deficiency in the pathogenesis of anaemia, in this case, anaemia that develops during the patient’s hospitalization." (PMID 36612220, 2022). "Still, anemia, CRP, and IL-6 were significantly associated with prematurity in SARS-CoV-2-infected pregnant women in our study." (PMID 36579593, 2022). "Although serum ferritin is often used clinically to assess the systemic iron status and the risk of anemia, ferritin is also an acute-phase protein produced in the body's inflammatory response to infection and injury, similar to CRP." (PMID 35711543, 2022). "We interpreted the resulting association of EDA-FN plasma levels with anemia, BM fibrosis, hs-CRP, and SVT as reflecting the critical role of EDA-FN in tissue repair, inflammation and vascular disease." (PMID 36212480, 2022). "Comparable with previous studies in other settings, low eGFR and high CRP were also associated with both the presence and the development of anaemia in this study." (PMID 34372781, 2021). "Though, erythrocyte zinc protoporphyrin IX is normally present at 0.5 μM, with a ratio of 1:40000 haemes, it can rise 10-fold in certain anaemias and iron deficients or depletes which is associated with high CRP levels and malaria immunity." (PMID 33571267, 2021). "Other studies have also shown an association of anemia with hypoalbuminemia, increased C-reactive protein and decreased BMI." (PMID 33529195, 2021). "IL-6 induces hepcidin and causes secondary anemia, promoting CRP production and inhibiting albumin production." (PMID 34117557, 2021). "Anemia was determined by hemoglobin < 110 g/L and classified into iron-deficiency and non-iron-deficiency anemia according to the levels of serum ferritin, C-reactive protein, and alpha-1-acid glycoprotein." (PMID 34684422, 2021). "We further explored the effects of a combination of single determinants (iron deficiency, low eGFR and high CRP) that were individually associated with the presence or onset of anaemia, as a sensitivity analysis." (PMID 34372781, 2021). "ID, VAD, ZnD, and sufficient vitamin B6 intake (intake ≥ RNI) were associated with anaemia in Chamwino; elevated acute phase proteins (CRP or AGP) were positively while serum lycopene was inversely associated with anaemia in Kilosa." (PMID 34066852, 2021). "We found that malaria (OR, 4.08 (2.18–9.68)), fever during the previous two weeks (OR, 1.71 (1.08–2.70)), and signs of inflammation (CRP > 5 mg/L) (OR, 1.65 (1.05–2.59)) were associated with anemia." (PMID 33801005, 2021). "In the univariate analysis, all the investigated markers of inflammation or anemia were significantly associated with complicated AD: CRP (p > 0.001), WBC (p = 0.009), and fibrinogen (p = 0.001), as well as decreased levels of Hb (p > 0.001)." (PMID 33572940, 2021).
anemia (continued). "We estimated the association between anemia and other factors in a multivariate logistic regression analysis, and we found that fever in the previous two weeks, malaria status, and inflammation status (CRP > 5 mg/L) were factors associated with anemia." (PMID 33801005, 2021). "Patients with iron deficiency anemia had higher CRP levels compared to those with pernicious anemia." (PMID 33810272, 2021). "This study explored a cohort of patients admitted to the emergency department with a particular interest in determining the frequency of anemia and inflammation and the association between hemoglobin (Hb) and C-reactive protein (CRP) concentrations." (PMID 34830693, 2021). "In this study, we found that very old adults with iron deficiency, low eGFR and high CRP at baseline had a higher risk of having anaemia." (PMID 34372781, 2021). "Still, our primary analyses are based on measurements of iron status, vitamin B12, folate, CRP and creatinine, which are direct measures or surrogates for the most commonly mentioned causes of anaemia in older persons." (PMID 34372781, 2021). "In a US cohort study of 1,290 patients with IBD including 463 patients with UC, monocytosis was positively associated with CRP, anemia, disease severity, hospitalization, surgery, emergency department visits, and annual financial health-care costs." (PMID 34797817, 2021). "Further, inflammatory markers such as c-reactive protein, tumor necrosis factor-alpha and interleukins are increased in patients with anemia and associated with an adverse prognosis after stroke." (PMID 34207841, 2021). "Fourth, since biochemical measurements associated with inflammation (e.g., CRP or ferritin) or with the type of anemia were only available in a minority of the participants, we were not able to study their relation with HRQoL in the context of MDS." (PMID 34476573, 2021). "In the 2216 participants (59% female, 30% anaemia) at baseline, iron deficiency, low eGFR and high CRP were individually associated with the presence of anaemia." (PMID 34372781, 2021). "Raised CRP, anaemia and low albumin were biochemical factors associated with all-cause mortality; with anaemia and low albumin also being associated with commencing systemic therapy." (PMID 33579772, 2021). "As infection can also cause anemia, and inflammation can affect measures of iron deficiency, it is important to account for corresponding markers of inflammation such as C-reactive protein (CRP) or alpha-1-acid glycoprotein when reporting prevalence." (PMID 33918630, 2021). "Haemoglobin, ferritin, and C-reactive protein concentrations were measured to determine anaemia, iron deficiency (ID) and iron deficiency anaemia (IDA) prevalence." (PMID 34066577, 2021). "In fact, only patients with both anemia and inflammation presented a significant association between Hb and CRP, particularly in hospitalized patients and in patients diagnosed with respiratory diseases." (PMID 34830693, 2021). "The strongest risk factors present at time of diagnosis, associated with TB related mortality, were: age > 70 years, Charlson comorbidity index > 1, alcohol abuse, weight loss, anemia, and C-reactive protein > 100 mg/L (p < .05)." (PMID 32497102, 2020). "Mean hemoglobin, ferritin adjusted for C‐reactive protein (CRP), serum iron, transferrin saturation, prevalence of anemia, iron deficiency, and iron deficiency anemia as well as anthropometrics were compared between the groups at baseline, 3, and 6 months." (PMID 32724619, 2020). "Only 9 (60%) of the laboratory tests, and patient age, contributed significantly to the GPs’ ability to diagnose an underlying cause of anaemia (CRP, ESR, ferritin, folic acid, haemoglobin, leukocytes, eGFR/MDRD, reticulocytes and serum iron)." (PMID 32736551, 2020). "C-reactive protein above 100 mg/L, anemia and weight loss at time of diagnosis were all associated with TB related mortality, this suggests prolonged and more advanced TB disease at time of diagnosis." (PMID 32497102, 2020).
anemia (continued). "Advanced stage (ISS stage III, P = 0.040), more severe anaemia (Hb < 90 g/L, P = 0.044) and elevated CRP (> 10 mg/L, P = 0.006) were independent risk factors for infection." (PMID 32972385, 2020). "Advanced ISS stage (ISS stage III), more severe anaemia (Hb < 90 g/L) and elevated CRP (> 10 mg/L) were identified as independent risk factors for infection." (PMID 32972385, 2020). "Anemia was associated with elevated CRP and a lower FEV1, parameters reflecting a more advanced disease, whereas ACT or gastrointestinal comorbidities did not correlate with anemia." (PMID 32922186, 2020). "The strongest risk factors present at time of diagnosis and associated with TB related mortality were age > 70 years, CCI ≥ 2, alcohol abuse, weight loss, anemia, and C-reactive protein > 100 mg/L at time of diagnosis (p < .05)." (PMID 32497102, 2020). "Some patients diagnosed with IgG4-RD exhibit severe clinical manifestations such as fever and excessive exacerbation of laboratory parameters associated with systemic inflammation such as anemia, hypoalbuminemia, and elevated CRP." (PMID 31951598, 2020). "In MCD, interleukin-6 (IL-6) plays an important role, which is considered to be closely associated with its clinical presentation, with symptoms such as fever, weight loss, anemia, and elevated C-reactive protein (CRP)." (PMID 32705358, 2020). "Advanced ISS stage, more severe anaemia and the elevation of CRP are independent risk factors of infection, which also have a strong impact on prognosis." (PMID 32972385, 2020). "First, a logistic univariate regression analysis was performed, and the results showed that age, anemia, decreased serum albumin level, elevated serum CRP levels, and summer were independent risk factors for peritonitis (p < 0.05)." (PMID 32781861, 2020). "It should be noted that the CRP level was also associated with severe anemia in logistic regression, with a borderline statistical significance (p = 0.064; OR: 1.008; 95% CI: 1.000–1.016)." (PMID 32240223, 2020). "Multivariate logistic regression analysis demonstrated that advanced stage (ISS stage III, P = 0.040), more severe anaemia (Hb < 90 g/L, P = 0.044) and elevated CRP (> 10 mg/L, P = 0.006) were independent risk factors for infections." (PMID 32972385, 2020). "Low Se, ID, and anemia all show a similar increasing prevalence with a lower estimated protein intake, while CRP was strongly associated with mainly ID." (PMID 32825781, 2020). "When calculating for associations between anemia and iron metabolism variables with immune activation upon admission, anemic patients had significantly higher CRP, IL-6 and PCT levels." (PMID 32751400, 2020). "The positive association between the ERIand CRP values and index reduction with increased albumin are conditions that areclassically described as limitations of anemia treatment with ESAs." (PMID 29742267, 2018). "Factors associated with significantly shorter OS included ISS 3, kidney disease, weight loss, anemia, thrombocytopenia, hypoalbuminemia, elevated β2-microglobuline and CRP." (PMID 29844872, 2018). "Among four potential variables extracted in univariate analysis, namely, total circumferential lesion, elevated CRP level, elevated white blood cell count, and anemia, the first two were revealed as risk factors for esophageal fistula in multivariate analysis." (PMID 29776344, 2018). "In multi-variable models, anemia was independently predicted by HbAS, HbSS, malaria, iron deficiency (ID; inflammation-adjusted ferritin <12 μg/L), higher C-reactive protein, lower plasma folate, and younger age." (PMID 28671630, 2017). "In a sensitivity analysis we found cytopenia (anemia, leukopenia and thrombocytopenia) to be significantly associated with haematological cancer, leucocytosis, thrombocytosis and elevated CRP were associated with solid cancer." (PMID 29197366, 2017).
anemia (continued). "Haemoglobin was lower despite the fact that men were characterized by an increased baseline CRP and a higher prevalence of co-morbidities, two acknowledged risk factors for anaemia severity." (PMID 28058668, 2017). "Inflammation, defined by an elevated CRP level, was very common among cases (82%), and thus it was identified as a major risk factor for anaemia." (PMID 28241813, 2017). "MS is characterized by a complex network of nutritional and metabolic disorders, including inflammation, oxidative stress, vitamin D deficiency, anaemia and high levels of C reactive protein (CRP) 3,4." (PMID 28492722, 2017). "Recurrent episodes of peritonitis, with negative culture, spontaneously regressed, in association with anemia, low albumin and high C-reactive protein, can be found in case of EPS." (PMID 27964725, 2016). "Inflammatory markers associated with greater severity of anaemia in both patient groups included increasing CRP, IL-1β and IL-6 concentrations." (PMID 26792471, 2016). "Anemia is associated with lower handgrip strength in community-dwelling older persons even after adjustment for inflammatory markers such as C-reactive protein, interleukin-6, and tumor necrosis factor-α25." (PMID 27549351, 2016). "Using univariate regression analysis, AGEs levels were positively associated with the presence of anemia and disease activity parameters such as CRP levels and ferritin levels in AOSD patients." (PMID 25956266, 2015). "Moderate disease activity (OR: 3.48, 95% CI, 1.95–9.64, P = 0.002) and elevated CRP levels (OR: 1.8, 95% CI, 1.04–3.11, P = 0.02) were independently associated with anemia." (PMID 25705682, 2015). "After adjustment for anemia, high CRP and creatinine, a significant positive association was found between the lowest FEV1/Ht3 quartile and physical decline with OR 1.89 (95%CI 1.05-3.39 p < 0.05)." (PMID 25888051, 2015). "Particularly in the setting of active disease and/or an increased CRP level, the suspicion of underlying anemia should be raised, which should be looked for carefully." (PMID 25705682, 2015). "Moderate disease increased 3.5-fold the risk of anemia, whereas each 1 mg/L increase in CRP increased this probability by 80%." (PMID 25705682, 2015). "A reverse association was found between C reactive protein and anemia, inflammation explaining the decline in hemoglobin." (PMID 25710019, 2015). "Some ICU studies reported an association of HD with serum max CRP levels, anemia, and neurologic disorders." (PMID 26347584, 2015). "In the univariable analysis older age (P < 0.001), critical limb ischemia (P = 0.012), anemia (P = 0.018), history of cardiovascular disease (P = 0.002), decreased eGFR (P < 0.001), and higher CRP values (P = 0.009) were significantly associated with MACE." (PMID 26321028, 2015). "In multivariate model, independent variables associated with anemia were moderate disease activity and CRP." (PMID 25705682, 2015). "It clearly shows that current anemia was strongly associated with both moderate disease activity and higher CRP levels." (PMID 25705682, 2015). "In multivariable models, risk factors for serum selenium deficiency were country, previous tuberculosis, anemia, and elevated C-reactive protein." (PMID 25401501, 2014). "Apart from her known iron deficiency anemia, laboratory studies revealed increased levels of C-reactive protein (CRP: 70 mg/L) and elevated erythrocyte sedimentation rate (ESR: 72 mm/hour)." (PMID 25434739, 2014). "Child's sex and C-reactive protein levels were associated with anaemia in the multivariable analysis." (PMID 24644526, 2014). "For both genders, Sub-Saharan African origin, diabetic nephropathy, lower mGFR, higher proteinuria and higher CRP levels were associated with lower Hb levels and higher prevalence of anemia." (PMID 24586229, 2014). "Other risk factors for baseline serum selenium deficiency were anemia, higher CRP concentrations and prior TB." (PMID 25401501, 2014).